RNU6-643P (RNA, U6 small nuclear 643, pseudogene)
Gene: Small nuclear RNA gene on chromosome 6 (41,302,466 to 41,302,572, reverse strand). Ensembl gene ENSG00000206745.
Homologues: Orthologues: chimpanzee U6 (97% identical), macaque U6 (89% identical), guinea pig U6 (84% identical), pig U6 (82% identical), rabbit U6 (80% identical), mouse Gm24378 (79% identical), rat LOC120097314 (77% identical). Paralogues in human: RNU6-1152P (89% identical), RNU6-589P (89% identical), RNU6-310P (88% identical), RNU6-393P (88% identical), RNU6-41P (88% identical), RNU6-44P (88% identical), RNU6-1060P (87% identical), RNU6-116P (87% identical), RNU6-15P (87% identical), RNU6-19P (87% identical), RNU6-211P (87% identical), RNU6-259P (87% identical), and 1286 more.